WNT3 (Wnt family member 3)
Diseases named in the same sentence as WNT3 in open-access papers (continued):
Sharing a sentence is not in itself a finding about the gene and the disease.
medulloblastoma (2 papers, 2010 to 2013). A malignant, invasive embryonal neoplasm arising from the cerebellum. "Immunoblotting showed a marked increase in P-ERK1/2 and P-ERK5 levels with WNT3 treatment in medulloblastoma cells." (PMID 24303070, 2013). "As observed with cerebellar GCPs, treatment of medulloblastoma cells with WNT3 decreased the expression of ATOH1." (PMID 24303070, 2013). "Immunolabeling with anti-P-ERK1/2 antibodies further showed that WNT3 treatment increased P-ERK1/2 in medulloblastoma cells." (PMID 24303070, 2013). "Importantly, WNT3 inhibits proliferation of medulloblastoma tumor growth in mouse models by a similar mechanism." (PMID 24303070, 2013). "Our finding that WNT3 is a potent suppressor of GCP growth and tumor formation in a mouse model of medulloblastoma suggests that WNT3 may have potential therapeutic value for the treatment of medulloblastoma in humans." (PMID 24303070, 2013). "Thus, WNT3 is a novel growth suppressor during cerebellar development and an important regulator of medulloblastoma formation." (PMID 24303070, 2013). "To define the signaling pathways involved in WNT3 inhibition of GCP and medulloblastoma growth, we examined whether WNT3 activates the canonical WNT/β-catenin signaling pathway." (PMID 24303070, 2013). "Importantly, WNT3 also suppressed medulloblastoma growth in vivo in a mouse model of medulloblastoma through mechanisms that involve activation of ERK1/2 and ERK5 signaling." (PMID 24303070, 2013). "In comparison, the genes Wnt3 and Wnt7a, which were found to be up-regulated by gene expression microarray analysis, were validated as up-regulated by real-time, RT-PCR and western blotting in SmoA1 +; Pten +/− medulloblastomas." (PMID 20520772, 2010). "Thus WNT3 is a potent inhibitor of medulloblastoma development." (PMID 24303070, 2013). "We were initially surprised that WNT3 inhibition of GCP proliferation and mouse medulloblastoma formation involved activation of ERK1/2 and ERK5." (PMID 24303070, 2013). "Here we identify WNT3 as a novel suppressor of GCP proliferation during cerebellar development and an inhibitor of medulloblastoma growth in mice." (PMID 24303070, 2013). "To examine whether WNT3 treatment activated ERKs in a mouse model of medulloblastoma, we measured P-ERK levels in purified tumor cells cultured for 24 h with WNT3 by immunoblotting and immunolabeling." (PMID 24303070, 2013). "Because WNT3 decreased GCP proliferation, we tested whether WNT3 also affected the formation of medulloblastoma in two mouse models." (PMID 24303070, 2013). "Here we examined the role of WNT3 in GCP proliferation and medulloblastoma growth." (PMID 24303070, 2013). "The present study identifies WNT3 as a novel extracellular regulator of GCP proliferation and differentiation during normal mouse cerebellar development, and as an inhibitor of tumor growth in a mouse model of medulloblastoma." (PMID 24303070, 2013).
memory impairment (2 papers, 2022 to 2025). "Our study fills this void by identifying a novel astrocyte‐mediated WNT3/IGF‐1 signaling axis in the dorsal DG as a critical mechanistic link between peripheral nerve injury and the concurrent development of nociceptive sensitization and memory impairment." (PMID 41414737, 2025). "Therefore, the activation of Wnt3/β-catenin signaling inhibits Aβ production and tau protein hyperphosphorylation and upregulates BDNF, which is necessary for synaptic plasticity and restoring learning and memory impairments." (PMID 36015156, 2022).
neuroblastoma (2 papers, 2016 to 2021). Neuroblastoma (NB) is the most common solid, extracranial childhood tumor. "In neuroblastoma N2a cells, the Wnt3 intensity at the cell membrane decreases with the Fzd7 downregulation." (PMID 33525513, 2021). "However, in terms of autocrine signals WNT3 and WNT5A were the most highly expressed Wnt ligands across all five neuroblastoma cell lines." (PMID 27531891, 2016).
non-small cell lung carcinoma (2 papers, 2014 to 2023). A group of at least three distinct histological types of lung cancer, including non-small cell squamous cell carcinoma, adenocarcinoma, and large cell carcinoma. "In non-small cell lung cancer (NSCLC), Wnt ligands (Wnt1, Wnt2, Wnt3, and Wnt5a) and other signaling modules (FZD8, PORCN, and TCF-4) are overexpressed." (PMID 37190019, 2023).
oral squamous cell carcinoma (2 papers, 2021 to 2024). "In addition, it has been reported that chrysophanol inhibits EMT formation and metastasis via a Wnt-3-dependent signaling pathway in oral squamous cell carcinoma." (PMID 34519612, 2021).
osteoporosis (2 papers, 2015 to 2024). A condition of reduced bone mass, with decreased cortical thickness and a decrease in the number and size of the trabeculae of cancellous bone (but normal chemical composition), resulting in increased fracture incidence. "The evidence taken together supported the importance of WNT3 and WNT9B in the Wnt signaling pathway in determining osteoporosis." (PMID 25811989, 2015).
prostate carcinoma (2 papers, 2021 to 2023). A carcinoma that arises from epithelial cells of the prostate gland. "In prostate cancer, TROAP also takes part in regulating WNT3/surviving signaling pathways to affect cell progression." (PMID 37731946, 2023).
Aleutian disease (1 paper, 2024). "From this, we identified several candidate genes contributing to the growth and feed efficiency (ARID1B, APPL1, TOX, and GPC5), reproduction (GRM1, RNASE10, WNT3, WNT3A, and WNT9B), pelt quality (MYO10, and LIMS1), and Aleutian disease tests (IFNGR2, APEX1, UBE3A, and STX11)." (PMID 38167844, 2024).
alopecia (1 paper, 2022). Hair loss usually from the scalp. "Transgenic mice overexpressing Wnt3 exhibited phenotypes such as short hair, alopecia, and abnormal differentiation of hair follicles." (PMID 36118352, 2022).
cervical cancer (1 paper, 2021). A primary or metastatic malignant neoplasm involving the cervix. "Based on this finding, we stimulated cervical cancer cells with L. iners metabolites lactate and lactate and 3-OBA and found that L. iners metabolites and lactate promoted expression of the Wnt pathway-related proteins wnt3 and β-catenin and the level of core fucosylation in epithelial cells." (PMID 34799549, 2021).
dysplasia (1 paper, 2007). A usually neoplastic transformation of the cell, associated with altered architectural tissue patterns. "The components of canonical Wnt pathway, such as Wnt3, β-catenin, and cyclin D1, were detected, implying that this pathway is potentially involved in the progression of dysplasia in oral leukoplakia." (PMID 17922924, 2007). "Thus, Wnt/β-catenin pathway is considered to be involved in the progression of dysplasia in oral leukoplakia, as shown by nuclear expression of β-catenin and other components, including Wnt3 and cyclin D1." (PMID 17922924, 2007). "Both the nuclear expression of β-catenin and Wnt3 expression were observed in oral leukoplakia with dysplasia, and therefore the aberrant Wnt signaling pathway may promote malignant transformation by triggering cyclin D1 expression and consequently uncontrolled progression into the cell cycle." (PMID 17922924, 2007).
emphysema (1 paper, 2018). "We implicated genes that are genetically regulated in known COPD-susceptibility loci, such as FAM13A, and also found genes in regions that were not previously reported: WNT3 for severe COPD, and DCBLD1 and LILRA3 for quantitative emphysema." (PMID 29566699, 2018).
Ewing sarcoma (1 paper, 2025). A small round cell tumor that lacks morphologic, immunohistochemical, and electron microscopic evidence of neuroectodermal differentiation. "Upregulated gene transcripts in Ewing sarcoma tumors developed in the hu-CD34+ models compared with the NSG model include Wnt3, Hox gene family members, and collagen family genes, some of which have been previously reported to be pro-tumorigenic in Ewing sarcoma." (PMID 40858520, 2025).
gastrointestinal adenomas (1 paper, 2022). "In gastrointestinal adenomas and differentiated carcinomas, Wnt3 and Wnt cargo receptor Evi/Wntless are significantly increased and crucial for cancer cell proliferation and colony formation, and we show that Wnt3 and Evi/Wntless co-localise on cytonemes." (PMID 36040316, 2022).
Insulin resistance (1 paper, 2020). Increased resistance towards insulin, that is, diminished effectiveness of insulin in reducing blood glucose levels. "Another mechanism by which insulin resistance or deprivation can compromise neurogenesis is via the Wnt3-NeuroD1 pathway." (PMID 33004912, 2020).
liver disease (1 paper, 2008). "We have identified eight potential FZD activating events, each occurring in a significant proportion of HCCs (⩾20%) – that is, upregulation of FZD3/6/7 and WNT3/4/5A, and repression of sFRP1/sFRP5 – which accumulate with severity of the liver disease and tumour stage." (PMID 18577996, 2008). "Of interest was the progressive accumulation of the FZD activating events (WNT3/4/5A and FZD3/6/7 upregulations and sFRP1/5 repression) with severity of the liver disease and the tumour stage." (PMID 18577996, 2008).
mood disorder (1 paper, 2023). A cognitive disorder a disturbance in which the person's mood is hypothesized to be the main underlying feature. "The eQTLs associated with the index level mood disorders are associated with MAPT, KANSL1 and WNT3 transcript levels." (PMID 37336921, 2023).
myeloma (1 paper, 2024). "WNT3 contributed to cell adhesion–mediated drug resistance (CAM-DR) of myeloma cells via the WNT/RhoA/ROCK pathway of myeloma cells in an autocrine manner." (PMID 38711026, 2024).
myopia (1 paper, 2016). "In this study, Wnt/β-catenin signaling pathway was mainly induced by Wnt3 to regulate experimentally induced myopia." (PMID 27247798, 2016). "Furthermore, our results on the potential relationship between FDM and Wnt3/β-catenin signaling pathway clearly suggest a potential target for preventing and treating scleral remodeling in myopia." (PMID 27247798, 2016). "Our study firstly demonstrated that Wnt3 was expressed in scleral fibroblasts from FDM, which was considered to mediate canonical Wnt/β-catenin signaling pathway in myopia." (PMID 27247798, 2016). "Therefore, Wnt3/β-catenin signaling pathway, as the upstream regulatory pathway, regulated the expression of TGF-β1 in scleral fibroblasts in experimental myopia." (PMID 27247798, 2016).
neural tumors (1 paper, 2013). "Thus, the present study suggests a novel role for WNT3 as a regulator of neurogenesis and repressor of neural tumors." (PMID 24303070, 2013).
Obesity (1 paper, 2021). Accumulation of substantial excess body fat. "Protein tyrosine phosphatase receptor type T is known to prevent obesity by regulating the metabolism in high-fat-diet mice, and metabolic imbalances reduce the expression of proto-oncogene protein WNT3 in obese and diabetic samples." (PMID 34561612, 2021).
oesophageal cancer (1 paper, 2023). "Another study found that circRNA_100367 can enhance the radioresistance of oesophageal cancer cells by regulating the miR-217/Wnt3 pathway." (PMID 37428781, 2023).
Oral leukoplakia (1 paper, 2007). A thickened white patch on the oral mucosa that cannot be rubbed off. "We examined the expression pattern of Wnt3 in oral leukoplakia." (PMID 17922924, 2007). "Wnt3 expression was detected in the epithelial cell membrane or cytoplasm in oral leukoplakia where nuclear expression of β-catenin was evident, but not in epithelial cells without nuclear expression of β-catenin." (PMID 17922924, 2007).
parathyroid tumors (1 paper, 2007). "Therefore, we examined the effect of DKK1, which is expressed in parathyroid tumors (unpublished data) on WNT3-stimulated β-catenin activity in sHPT-1 cells." (PMID 18044981, 2007). "WNT3 but not WNT1 was expressed by RT-PCR in parathyroid tumors." (PMID 18044981, 2007).
periodontitis (1 paper, 2025). An acute or chronic inflammatory process that affects the tissues that surround and support the teeth. "By analyzing the GEO databases GSE223924 and GSE85195 we found that the Wnt ligands Wnt3, Wnt3a, Wnt5b and Wnt7b are transcriptionally upregulated in periodontitis and OSCC, especially during early carcinogenic phases." (PMID 40421179, 2025). "Together, it was found that Wnt ligands Wnt3, Wnt3a, Wnt5b and Wnt7b are concomitantly upregulated in periodontitis and oral carcinogenesis." (PMID 40421179, 2025). "Interestingly, the transcriptional upregulation of Wnt3, Wnt3a, Wnt5b and Wnt7b in periodontitis (GSE223924) was also observed in oral carcinogenesis (GSE85195)." (PMID 40421179, 2025). "Transcriptomic Z-score analysis shows that among 19 Wnt ligands available, two canonical Wnt ligands (Wnt3 and Wnt3a) and two non-canonical Wnt ligands (Wnt5b and Wnt7b) are upregulated in periodontitis." (PMID 40421179, 2025).
psoriasis (1 paper, 2012). An autoimmune condition characterized by red, well-delineated plaques with silvery scales that are usually on the extensor surfaces and scalp. "However, the repression of Wnt3 as well as the dysregulation of SFRP1 and SFRP2 are only found in invasive cutaneous SCC, but not psoriasis." (PMID 22384081, 2012).
radiation sickness (1 paper, 2022). "Up-regulation of FDXR and DDB2 GE indicates risk of mild acute radiation sickness, whereas an up-regulation of FDXR and DDB2 combined with a down-regulation of WNT3 and POU2AF1 predicts severe ARS10,11." (PMID 35680903, 2022). "Specific radiation-sensitive genes (such as FDXR, DDB2, WNT3, POU2AF1) have become well established for biodosimetry purposes and acute radiation sickness (ARS)-prediction." (PMID 35680903, 2022).
rectal tumors (1 paper, 2015). "The Wnt3 has been reported in the HepG2 (liver), A549 (lung), MKN45 (gastric), breast and rectal tumors, and it belongs to the Wnt1 class of ligands and canonical Wnt/β-catenin pathway." (PMID 26498690, 2015).
seminoma (1 paper, 2015). A radiosensitive malignant germ cell tumor found in the testis (especially undescended), and extragonadal sites (anterior mediastinum and pineal gland). "Accordingly, WNT3 /5B and FZD7 expression is higher in EC tissues than in CIS /seminomas." (PMID 26226633, 2015).
small intestinal adenomas (1 paper, 2021). "Therefore, we focused on the possibility that deficiency of PC-derived Wnt3 in small intestinal adenomas might be the cause of reduced tumor multiplicity upon PC depletion." (PMID 33372038, 2021).
Stroke (1 paper, 2021). Sudden impairment of blood flow to a part of the brain due to occlusion or rupture of an artery to the brain. "SNP rs2074404 in WNT3 is associated with a family history of stroke." (PMID 33935957, 2021).
uveitis (1 paper, 2018). An inflammatory process affecting a part of or the entire uvea. "A homolog of WNT16, WNT3 (ENSP00000225512) was also predicted to participate in uveitis-specific pathogenesis." (PMID 30349554, 2018). "Therefore, speculating that WNT16 and WNT3 may be functionally related to uveitis is reasonable." (PMID 30349554, 2018). "According to recent publications, our inferred genes (WNT2, WNT16, WNT3, WNT7A, and WNT7B) are functionally related to the initiation and progression of uveitis due to their interference to the proliferation of urea and mixed immune cells." (PMID 30349554, 2018).
Werner syndrome (1 paper, 2024). "By analyzing the molecular alterations in mouse model with accelerated aging phenotypes due to loss of p21 function in a Werner syndrome background, we observed that Wnt3 and β-Catenin were down-regulated, while Notch1 and Hes1 were up-regulated." (PMID 39341834, 2024).
tumor (50 papers, 2008 to 2025). "It was an autocrine effect; a high level of adhesion was associated with an intense expression of WNT3 in tumor cells." (PMID 37239457, 2023). "Tumor-derived extracellular vesicles (TEVs) include RNA and a variety of cytokines such as TGF-β, activated Src, Wnt3, HIF1α, in which the process also associates with tumor progression." (PMID 33224886, 2020). "Herein, LAT1 deficiency played a role in tumor initiation by reduction of Wnt3." (PMID 36739585, 2023). "Wnt family member 3 (Wnt3) is a key signaling protein in the Wnt signaling pathway and is crucial in tumor development and progression." (PMID 38709402, 2024). "Wnt3 is directly present at the initiation phase, with Wnt2 appearing at the end to support the proliferation of cells in the tumour." (PMID 38397199, 2024). "Conditional deletion of LAT1 resulted in a reduced number of Paneth cells and decreased Wnt3 production while suppressing tumor development and promoting apoptosis, which benefited ApcMin/+ mice with a small number of small-sized tumors." (PMID 36739585, 2023). "By activating the WNT/β-catenin pathway, WNT3 plays a shaping role in tumor proliferation, migration and invasion, and functions in a variety of pathological processes including inflammation, metabolism, neurological development, and fibrosis processes." (PMID 37636041, 2023). "In conclusion, elevated levels of Wnt3 are essential for quickly proliferating gastrointestinal cancers; however, it is unclear how this hydrophobic ligand is disseminated within a tumour’s context." (PMID 36040316, 2022). "In many gastric carcinomas, Wnt3 expression is elevated compared with normal gastric epithelium, leading to increased proliferation in the tumour mass." (PMID 36040316, 2022). "Conversely, WNT5A, WNT7B, WNT2, WNT7A, WNT10A and WNT3 were tumor-positive WNTs, which significantly increased in many carcinomas." (PMID 35850748, 2022). "Hh and Wnt pathways activation was assessed by immunohistochemistry (Gli1 and beta-catenin) on corresponding tumor tissues, and by plasma concentrations of Shh and Wnt (Wnt1, Wnt2 and Wnt3) at ICI introduction and at the first clinical evaluation." (PMID 33807552, 2021). "Overall, our studies establish that cells of PC lineage, through Wnt3 production, play an important role in early tumor development in the intestine." (PMID 33372038, 2021). "One of the most interesting pathways of miR-491-5p as a tumor suppressor is by targeting the Wnt3/β-catenin pathway mediated via Foxi1." (PMID 34590612, 2021). "Consistently, the mRNA levels of these genes were all downregulated in tumor tissues formed by Wnt3-shRNA cells on nude mice." (PMID 31632267, 2019). "In our study, the difference of Wnt3 expression remains insignificant between tumors tissue and adjacent non-tumor tissue." (PMID 30814912, 2019). "Knockdown of Wnt3 in human CRC cells delayed tumor formation in nude mouse xenografts through silencing of canonical Wnt pathway and glycolysis." (PMID 31632267, 2019). "While on the contrary, mRNA levels of HK2 and LDHA genes were elevated in tumor tissues formed by Wnt3-pEX4 cells." (PMID 31632267, 2019). "Collectively, these data demonstrated that the Wnt3 plays a tumor-promoting role in the development of CRC." (PMID 31632267, 2019). "Expression levels the remaining Wnt ligands, including Wnt1, Wnt3, Wnt4, Wnt5A, Wnt8A, Wnt9B, Wnt10A and Wnt16, remained insignificantly different between liver tumors tissues and adjacent non-tumor tissues." (PMID 30814912, 2019). "To target this R/Z-/- tumor vulnerability, we developed selective inhibitors for Wnt3/3a-mediated signaling." (PMID 30664649, 2019).